EML4 (EMAP like 4)
Diseases named in the same sentence as EML4 in open-access papers (continued):
Sharing a sentence is not in itself a finding about the gene and the disease.
lung cancer (continued). "Therefore, a 75‐bp insertion between exons 24 and 25 besides EML4‐ALK rearrangement of resected primary lung cancer after second‐generation ALK‐TKI treatment may reflect a possible resistant mutation." (PMID 31285825, 2019). "Fusion between EML4 (echinoderm microtubule associated protein-like 4), a microtubule-associated protein, and ALK (anaplastic lymphoma kinase), a tyrosine kinase receptor belonging to the insulin receptor superfamily, was the first oncogenic fusion to be detected in lung cancer." (PMID 28872581, 2017). "The echinoderm microtubule-associated protein-like 4 - anaplastic lymphoma kinase gene (EML4-ALK) fusion oncoprotein, which arises from an inversion within chromosome 2p and results in constitutive kinase activity by dimerization of ALK, represents a major molecular target in lung cancer." (PMID 26219569, 2015). "In addition to the EML4-ALK fusion gene in lung cancer, various ALK-related diseases have been reported, including familial neuroblastoma, renal cell carcinomas, esophageal squamous cell carcinomas, breast cancer, colonic adenocarcinomas, glioblastoma multiforme, and anaplastic thyroid cancer." (PMID 25941796, 2015). "Of the 3 histopathologically confirmed ALK fusion partners in lung cancer, EML4 colocalizes with microtubules and may contribute to the stabilization of microtubules, KIF5B moves on the microtubules as a kinesin heavy chain, and KLC1 binds to kinesin heavy chains as a kinesin light chain." (PMID 22347464, 2012). "ALK fusions, such as the classic EML4‐ALK, are known drivers of lung cancer and effective therapeutic targets." (PMID 40151836, 2025). "EML4-ALK fusions, RET rearrangements, ROS1 fusions, and NTRK1/2/3 fusions are observed at a cumulative frequency of 3 %–10 % in lung cancers." (PMID 40503459, 2025). "Among lung cancer cells, NCI-H3122 cells with EML4-ALK v1 tended to be more sensitive to ALK TKIs than NCI-H2228 cells with EML4-ALK v3a/b." (PMID 38829559, 2024). "Several studies reported the presence of both EML4-ALK and EGFR rearrangements in patients with lung cancer." (PMID 39695132, 2024). "The oncogenic receptor tyrosine kinases are key to lung cancer malignant transformation, as evidenced by the clinical successes of EGFR, MET, and EML4-ALK inhibition by small molecule therapeutics." (PMID 38827327, 2024). "Understanding the role of LLPS in regulating the function of EML4-ALK and its downstream signaling pathways is expected to contribute to the development of novel therapeutic approaches for lung cancers with ALK fusions." (PMID 37705755, 2023). "While extensive studies have explored the oncogenic properties of EML4-ALK, the involvement of LLPS in regulating its function and contributing to lung cancer development has recently gained attention 100,101." (PMID 37705755, 2023). "Case 1 showed EML4-ALK fusion, which most commonly occurs in lung cancer, accounting for approximately 3–5% of all non-small cell lung cancers (NSCLC)." (PMID 36915094, 2023). "Alvocidib effectively inhibits EML4-ALK cells, driving lung cancer progression, thereby suppressing tumor growth and inducing apoptosis." (PMID 38116825, 2022). "used CRISPR/Cas9 (clustered regularly spaced short palindrome repeats/CRISPR related protein 9) gene to induce EML4-ALK rearrangement in animal models, which also induced lung cancer." (PMID 36591504, 2022). "Approximately 85% of lung cancer patients present with NSCLC and patients positive for the EML4-ALK fusion gene represent a subpopulation of these." (PMID 34633654, 2022). "As the most common fusion type of ALK, EML4-ALK is responsible for the growth and survival of lung cancer cell lines and functions as a therapeutic target in NSCLC." (PMID 36523965, 2022). "F-circEA is extracted from EML4-ALK fusion gene and is a common example for lung cancer circRNAs, while expression of F-circEA gene can be detected in plasma samples of lung cancer patients." (PMID 35188072, 2022).
lung cancer (continued). "Our study extended the spectrum of ALK fusion partners in ALK + NSCLC, and we reported a new ALK fusion: ALK-GCA and EML4-ALK and its sensitivity to alectinib firstly in lung cancer." (PMID 35070986, 2022). "Accordingly, several oncogenic genes have been used as biomarkers for lung cancer diagnosis; however, the sensitivities of K-ras-G12C, EGFR, EML4-ALK, and CLIP1-LTK in lung cancer patients are only 14%, 46%, 4%, and 0.5%, respectively." (PMID 35574342, 2022). "EML4‐ALK expression was induced in GEM mice (n = 3) by daily doxycycline feeding, tumors developed in situ, and lung cancer progression was monitored by computed tomography (CT)." (PMID 34845836, 2022). "For example, an expected EML4-ALK fusion and an unexpected AGK-BRAF fusion was detected in a lung cancer sample harboring a known EML4-ALK fusion at Laboratory A during the TST170 validation and was confirmed by orthogonal testing with a different NGS assay." (PMID 34093633, 2021). "EML4-ALK translocation results in constitutive ALK tyrosine kinase activity, representing an oncogenic addiction pathway in lung cancer." (PMID 33806977, 2021). "To explore the mechanisms involved in the transformation of lung cancer cells triggered by EML4-ALK, we used microarray analysis to generate gene expression profiles for H2228 cells transfected with siRNA-NC or siRNA-EML4-ALK." (PMID 34090412, 2021). "Trametinib is an MEK1 inhibitor for treating EML4-ALK-positive, EGFR-activated, and KRAS-mutant lung cancers." (PMID 32245216, 2020). "To investigate the correlation between an EML4-ALK rearrangement and PEM sensitivity, we first evaluated the protein expression of ALK in four lung cancer cell lines by Western blotting." (PMID 31795298, 2019). "The discovery of the EML4-ALK fusion kinase in 2007 was a breakthrough for this situation, and kinase fusion genes now form a group of relevant targetable oncogenes in lung cancer." (PMID 30941048, 2019). "We were particularly interested in the intron 19 region (I19) of ALK, since portions of I19 have been found in the mRNA transcripts of two ALK fusion genes, EML4-ALK and PPFIBP1-ALK, detectable in lung cancer and myofibroblastoma, respectively." (PMID 29535836, 2018). "According to data derived from studies of lung cancer, EML4-ALK fusion occurs through a paracentric inversion within the short arm of chromosome 2, where EML4 and ALK genes are both located." (PMID 28535796, 2017). "In NSCLC (Human non-small cell lung cancers), an oncogene namely EML4-ALK is present, and CRISPR–cas9 system was used to create a mouse model of Eml4-Alk-driven lung cancer." (PMID 27725818, 2016). "The aim of this study is to investigate the methylation status of the SOCS3 promoter in EML4-ALK-positive H2228 cells and lung cancer tissues." (PMID 27666544, 2016). "At present, crizotinib, a dual inhibitor of EML4-ALK and MET, already has been widely employed in lung cancer patients harboring the EML4-ALK fusion." (PMID 26919104, 2016). "Here, we report an EML4-ALK positive non-small cell lung cancer (NSCLC) in a patient previously diagnosed with T cell lymphoma and review literature on metachronous lung cancer complicating with lymphoma." (PMID 25676402, 2015). "Since the incidence of EML4-ALK is low in NSCLC patients, it is necessary to elucidate clinicopathological characteristics of the EML4-ALK fusion gene-positive lung cancer to improve screening efficiency." (PMID 25706305, 2015). "The EML4-ALK fusion, initially identified in lung cancer has since been reported in breast cancer, colorectal carcinomas, and in pediatric renal medullary carcinoma that affects young African–Americans with the sickle cell trait." (PMID 26684754, 2015). "Despite the relatively low frequency of the EML4-ALK fusion, ALK-rearranged lung cancer is a unique molecular subgroup with a high sensitivity to ALK inhibitors, and is mutually exclusive from other well-known oncogenic mutations involving EGFR or KRAS." (PMID 23922677, 2013).
lung cancer (continued). "In lung cancer, 3 fusion partners of ALK have been reported—EML4, TFG, and KIF5B—although the presence of TFG-ALK in lung cancer has not yet been proven with histopathological evidence." (PMID 22347464, 2012). "An inversion event on the short arm of chromosome 2, resulting in the fusion of ALK gene with the EML4 gene locus, is the most common aberration of the ALK gene in lung cancer." (PMID 22825000, 2012). "In lung cancer, the well-developed epidermal growth factor receptor (EGFR) and the newly emerging EML4-anaplastic lymphoma kinase (ALK) are important therapeutic targets." (PMID 23109866, 2012). "The identification of the EML4-ALK fusion gene in nonsmall cell lung cancer (NSCLC) was reported in 2007, and within 3 years ORR of 57% and median 6 months PFS of 72% in pretreated patients with NSCLC with the EML4-ALK translocation was reported." (PMID 22701804, 2012). "The first to be discovered were in prostate cancer, where about half of all cases have the TMPRSS2-ERG fusion gene, and lung cancer, where around 5% of lung cancers have a fusion that activates the ALK tyrosine kinase, the EML4-ALK fusion." (PMID 23260012, 2012). "Targeted therapeutic approaches for lung cancer, including treatment with TKIs for EGFR or the fusion protein EML4-ALK, have seen substantial progress over the last few years." (PMID 21847121, 2011). "Lung cancer patients with ALK and EML4 fusions respond significantly to ALK inhibitors." (PMID 40136367, 2025). "Additionally, this case revealed the presence of an EML4 (exon 6):: ALK (exon 20) (V3) fusion, which was one of the most common genetic alterations observed in lung cancer." (PMID 40224190, 2025). "Although specific somatic mutations—such as those in EGFR, KRAS, and EML4-ALK—have been identified, particularly in lung adenocarcinoma, they are absent in the majority of patients with lung cancer." (PMID 41241099, 2025). "For example, disrupting EML4-ALK LLPS and impairing STAT3 phosphorylation may be a novel treatment for EML4-ALK-positive lung cancer." (PMID 40642070, 2025). "Based on assay design and coverage of key intronic regions of the genome, we were also able to detect a broad range of clinically relevant fusions, such as EML4::ALK, RET, and ROS1 rearrangements with diverse gene partners in lung carcinomas, BRAF::KIAA1549 and EGFRvIII alterations in gliomas." (PMID 39289779, 2024). "EML4‐ALK lung cancer patients do not necessarily express only one secondary mutation but can express double and even triple mutations such as S1206F/G1202R/G1269A simultaneously as a scheme of increasing on‐target resistance." (PMID 37149843, 2023). "As xenograft mouse models cannot fully mimic the complex microenvironment of lung cancer initiation and development in vivo, we next established a GEM model with lung‐specific doxycycline‐inducible EML4‐ALK expression to further evaluate the activity of XMU‐MP‐5 in vivo." (PMID 34845836, 2022). "Similarly, in lung cancer, an oncogenic fusion of EML4/ALK generated a fusion circRNA, F-circEA-2a, which was shown to exhibit tumor promotion properties in lung cancer development." (PMID 35205610, 2022). "In this review, we look specifically at cancers driven by the EML4-ALK protein that is present in around 5% of lung cancer patients, occurring more frequently in young non-smokers." (PMID 35884511, 2022). "Lastly, removal of the gene fusion features (‘fusion’) resulted in a large decrease in recall for Lung_SmallCell (50% to 38%) likely as EML4-ALK fusions are characteristic of non-small cell (but not small cell) lung cancer." (PMID 35817764, 2022). "Other studies have found ceritinib and paclitaxel to be highly synergistic in the treatment of lung cancer cells with activation of the FAK even if they do not express EML4-ALK fusions." (PMID 35656694, 2022).
lung cancer (continued). "The less frequent EML4(e21)::ALK(e20) variant is not covered by the Idylla’s fusion-specific detection, which is designed to catch the most relevant gene fusions in lung cancer." (PMID 35237889, 2022). "In another report, the gene fusions of six never-smoking female patients with lung cancer were analyzed by RNA-Seq; these patients had no mutations in KRAS or EGFR and were negative for EML4-ALK." (PMID 33809651, 2021). "Of note, we also found induction of autophagy, although to a clearly lesser degree, in EML4-ALK negative A549 lung cancer cells treated with Ceritinib but not with Alectinib or Lorlatinib." (PMID 33907223, 2021). "However, it is intriguing that ML111 potently inhibited the EML4-ALK fusion-driven H3122 and KRAS/PI3KCA-mutant H460 lung cancer cell lines." (PMID 34683845, 2021). "The assay also enabled the detection of a EML4-ALK fusion (TI, RI) in a lung cancer patient." (PMID 33947144, 2021). "The discovery of the EML4-ALK fusion gene in a limited subset of patients affected by NSCLC and the subsequent clinical development of crizotinib in 2011 has been an impressive milestone in lung cancer research." (PMID 33352844, 2020). "We demonstrated that the transcription levels of ALK- or RET-fusion partner genes, such as EML4, CCDC6 and KIF5B, were constitutively activated in lung cancer cells, and the expression at the C-terminal region of ALK, RET, or ROS1 was also markedly elevated in each fusion-positive lung cancer cell." (PMID 30943926, 2019). "We found that the promoter of EML4 was constitutively activated in lung cancer as well as normal cells independent of ALK fusion, and C-terminal ALK protein level and phosphorylation were specifically elevated in ALK fusion–positive cancer cells." (PMID 30943926, 2019). "Portraying the spectrum of tumor recurrence mutations in the same patient without the oncogenic lung cancer driver mutations such as EGFR, KRAS, and EML4‐ALK is an integrative step of understanding lung cancer tumor progression." (PMID 30941903, 2019). "To identify other cancer samples that express EML4-ALK fusion transcripts, we reanalyzed our collection of 96 lung cancer samples with FuseFISH, a single-molecule fluorescence in situ hybridization (sm-FISH)–based method for the detection of fusion transcripts." (PMID 30718424, 2019). "PEM also induced the protein expression of TS irrespective of EML4-ALK status among the lung cancer cell lines." (PMID 31795298, 2019). "The aerrant methylation of the SOCS3 promoter region in EML4-ALK (+) H2228 cells and lung cancer tissues may be significantly involved in the pathogenesis of EML4-ALK-positive lung cancer." (PMID 27666544, 2016). "Clinical features of EML4-ALK-positive lung cancer include onset at a younger age and a history of no to light smoking." (PMID 26964537, 2016). "In addition we also sought for EML4-ALK translocation, which has been extensively reported in lung cancer." (PMID 26384210, 2015). "Although fusion gene EML4-ALK was originally discovered in lung cancer, it had not been discovered in other cancers before their study." (PMID 24533689, 2014). "In our case, although the bilateral adenocarcinomas have bronchioloalveolar pattern in common, the right lung cancer was EML4-ALK positive while the left one was not." (PMID 23617234, 2013). "The clinical features of lung cancer that harbors EML4-ALK include light- or never-smokers, younger age, adenocarcinomas with acinar pattern or signet ring adenocarcinoma, and a lack of EGFR or KRAS mutations." (PMID 23181703, 2012). "Importantly, in some cell lines harboring EML4-ALK fusions, targeting of ALK using specific inhibitors has shown promising efficacy for treatment of lung cancer through inhibition of Akt and induction of apoptosis." (PMID 20624322, 2010).
lung cancer (continued). "In lung cancer, the primary ALK fusion detected was identified as EML4-ALK, followed by TFG-ALK and KIF5-ALK, although other unknown fusions may also exist which can not be detected due to limits of present technology." (PMID 20624322, 2010). "Only one of the lung cancer samples tested positive for the EML4–ALK fusion transcript, whereas none were detected in 555 gastrointestinal and 90 breast cancer cases." (PMID 18414414, 2008). "Here we apply pseudo-random pulsatile optogenetic stimulation, live-cell imaging, and information theory to compare the information capacity of receptor tyrosine kinase (RTK) signaling pathways in EML4-ALK-driven lung cancer cells (STE-1) and non-transformed lung epithelial cells (BEAS-2B)." (PMID 40654619, 2025). "Here, we apply pseudorandom pulsatile optogenetic stimulation, live-cell imaging, and information theory to compare the information capacity of receptor tyrosine kinase (RTK) signaling pathways in EML4-ALK-driven lung cancer (STE-1) and in non-transformed (BEAS-2B) cells." (PMID 41214145, 2025). "However, it still remains largely unknown about how EML4–ALK fusion exactly fires downstream signaling and drives lung cancer formation." (PMID 33976114, 2021). "In exactly the same way, rapamycin sensitized crizotinib-resistant EML4-ALK+ lung cancer cells to ALK inhibition: Crizotinib alone did not affect ALK and AKT activity, but blocked the feedback activation from mTOR to AKT, when administered together with rapamycin." (PMID 29755689, 2018). "Lung cancer in non-smokers has many unique clinical, pathological and genetic features, which include dominant adenocarcinoma subtype, more frequent in women, higher frequency of EGFR and EML4-ALK mutations, and family history of lung cancer." (PMID 29137177, 2017). "Similarly, crizotinib showed stronger inhibition of lung cancer cell lines with a recurrent gene fusion between EML4 and ALK than it did in those without the fusion gene." (PMID 27070423, 2016). "KIF5B-RET is reported in a low percentage of lung cancers and is more frequent in non-smokers, in patients with adenocarcinoma, and exists exclusively with other mutations, such as EGFR, Kras, Braf, ErbB2 or EML4/ALK fusions." (PMID 25047660, 2014). "The EML4-ALK gene fusion was detected in only 4–8% of lung cancers mainly in light smokers or nonsmokers, and was the known driver factor of lung cancer." (PMID 35096611, 2021). "ALK (EML4-ALK is a well-known fusion oncogene) translocations are more frequent in nonsmokers’ than in smokers’ lung cancer." (PMID 32030321, 2020). "Despite the successful development of EGFR- or EML4-ALK-targeted TKIs, treatment options remain limited for patients with advanced lung cancer lacking an identifiable oncogenic driver alteration." (PMID 28806950, 2017). "The effect of this mutation was dramatically less vs. all drugs when it was introduced instead to EML4-ALK, likely explaining why it has never been reported in resistant ALK+ lung cancer." (PMID 27009859, 2016). "Two lung cancer cell lines, NCIH3122 and NCIH2228, were used as positive controls for EML4–ALK fusion and A549 cells were used as the negative control." (PMID 24406431, 2014). "We developed a 5′-rapid amplification of cDNA ends-based system optimized for FFPE tissues and evaluated this system on a lung cancer tissue with ALK rearrangement and without the 2 known ALK fusions EML4-ALK and KIF5B-ALK." (PMID 22347464, 2012). "For example, F-circEA, but not its host linear mRNA, could be detected in EML4–ALK+ lung cancer plasma; thus, circulating F-circEA would be a novel biomarker to detect EML4–ALK fusion and to determine an effective treatment for EML4-ALK+ patients." (PMID 35453621, 2022). "However, compared to the results in lung cancer, the partners of the ALK fusions in our study were totally different, and none of them were the canonical type (EML4-ALK)." (PMID 36612279, 2022).